BRAF (B-Raf proto-oncogene, serine/threonine kinase)
Diseases named in the same sentence as BRAF in open-access papers (continued):
Sharing a sentence is not in itself a finding about the gene and the disease.
Intellectual disability (8 papers, 2019 to 2025). "It is noteworthy, however, that patients harboring BRAF KE mutations exhibit severe intellectual disability." (PMID 39964758, 2025). "One novel variant (p.T599I) in the BRAF gene was identified in a girl with macrocephaly, hypertelorism, dark-colored moles, developmental delays, intellectual disabilities, ventricular septal defect, and focal septal hypertrophy." (PMID 30732632, 2019). "Specifically, in terms of neurodevelopmental functions, patients with mutations in the MAP2K2 gene show a lower incidence of intellectual disability (ID) compared to those with mutations in other genes, such as BRAF and MAP2K1, with an incidence rate of only 25%." (PMID 39982946, 2025). "Variants in genes such as BRAF and CNTNAP2 were associated with severe protein destabilization and phenotypic abnormalities, including encephalopathies and intellectual disabilities." (PMID 40282380, 2025). "Intellectual disability is reported to be more common in CFCS, which is associated with variants in BRAF (~75% of the CFCS cases), MAP2K1 and MAP2K2 (~25%), and KRAS (<2–3%)." (PMID 36012976, 2022). "The prevalence of intellectual disability is higher in BRAF (90%) than in other NSSDs (6% to 28%)." (PMID 36012976, 2022).
invasive carcinoma (8 papers, 2012 to 2025). A carcinoma that is not confined to the epithelium, and has spread to the surrounding stroma. "BRAF mutations, particularly V600E, are linked to indolent disease behaviour and a reduced risk of progression to invasive carcinomas." (PMID 39941911, 2025). "For comparison, KRAS and BRAF mutations are rarely detected in high-grade invasive carcinomas but are often present in borderline ovarian tumors, low-grade adenocarcinomas, and adjacent benign epithelium." (PMID 23344037, 2013). "These clinical behaviors of BRAF V600E were recapitulated in transgenic mice in which induced expression of BRAF V600E in the thyroid gland caused PTC that progressed to poorly differentiated invasive carcinomas." (PMID 27863429, 2017). "In the majority of cases with KRAS or BRAF mutations, high c-MYC expression was consistently observed in lesions with low grade intraepithelial neoplasia to invasive carcinomas." (PMID 23045412, 2012).
melanocytic neoplasm (8 papers, 2009 to 2026). "Most melanocytic neoplasms show oncogenic mutations in components of the MAPKinase cascade, particularly in BRAF and NRAS." (PMID 19718445, 2009). "Moreover, the pathogenic variants in NRAS and BRAF were also identified in the other melanocytic neoplasms, including congenital melanocytic nevi." (PMID 34643354, 2021). "pTERTm are suggested to have synergistic effects to promoter tumour cell proliferation with activating BRAF or NRAS mutations, which have been proposed to be driver mutations in the development of cutaneous melanocytic neoplasms." (PMID 26799744, 2016). "Examples of other, less common, mechanisms underlying hyperactivation of the ERK pathway in melanocytic neoplasms include activating mutations in MEK kinases, overexpression of wild-type BRAF and decreased expression of negative regulators of the pathway." (PMID 25413220, 2014). "This study assessed BRAF mutational status using IHC for BRAF V600E and competitive allele-specific real-time PCR (CAST-PCR) in 50 formalin-fixed paraffin-embedded (FFPE) tissue blocks representative of melanocytic neoplasms." (PMID 36737739, 2023). "A recent study has reported frequent somatic mutations in the heterotrimeric G protein α-subunit (GNAQ) in a subset of melanocytic neoplasms which do not present alterations in the RAS or BRAF genes." (PMID 19718445, 2009).
melanoma in situ (8 papers, 2022 to 2026). "Of the 41 patients with melanoma in situ, 60.9% had a BRAF mutation, and in patients with lentigo maligna (LM), only one patient (3.6%) had a BRAF mutation detected." (PMID 39200941, 2024). "There was a statistically significant correlation between a melanoma in situ diagnosis and the presence of a BRAF mutation (χ2 test, χ2 = 29.17, p < 0.0001)." (PMID 39200941, 2024). "Concerning the association of specific mutations with clinical characteristics, a higher trend of BRAF V600E was linked to low Breslow thickness (<1 mm) or in situ melanomas." (PMID 36765773, 2023). "In our study, we have observed BRAF mutation only in one in situ carcinoma sample that simultaneously possessed the MSI-H phenotype." (PMID 35173208, 2022).
sarcoidosis (8 papers, 2020 to 2025). Sarcoidosis is a multisystemic disorder of unknown cause characterized by the formation of immune granulomas in involved organs. "Sarcoidosis can be triggered by treatments such as ICIs, BRAF/MEK inhibitors, and tumor necrosis factor-alpha (TNF-α) blockers." (PMID 39717410, 2024). "BRAF and MEK inhibitors (dabrafenib, vemurafenib and trametinib, cobimetinib) are also associated with sarcoidosis." (PMID 33807303, 2021). "Clinicians should be aware of the potential for exacerbation of sarcoidosis when transitioning from immune-checkpoint inhibitors to these novel BRAF-dimerisation inhibitors, particularly as their uptake in treating cancers increases beyond clinical trials." (PMID 35663773, 2021). "Recent cancer immunotherapies, including immune checkpoint inhibitors (targeting PD-1, PD-L1, or CTLA-4) and BRAF or MEK inhibitors were also reported as possible inducers of sarcoidosis-like reactions." (PMID 33330555, 2020). "These SLRs are clinically indistinguishable from primitive sarcoidosis and occur in close temporal association with the start of an offending drug, typically checkpoint inhibitors like PD-1 or BRAF-targeted therapies." (PMID 39717410, 2024). "The description of various side effects, including sarcoidosis, has come with the recent advent of immune checkpoint inhibitors (ICI), as well as BRAF/MEK inhibitors." (PMID 33330555, 2020).
serous cystadenoma (8 papers, 2016 to 2025). A serous neoplasm in which the cysts and papillae are lined by a single layer of cells without atypia, architectural complexity or invasion. "The acquisition of KRAS or BRAF and possibly other mutations including PAX-2 in OEIs and serous cystadenomas result in their gradual transformation to serous borderline tumors and ultimately LGSC." (PMID 30949203, 2019). "LGSC characterized by KRAS, BRAF, and ERBB2 gene mutations is thought to show stepwise progression and develop from serous cystadenomas and SBT." (PMID 29321056, 2018). "More specifically, serous cystadenomas do not have mutations in either KRAS or BRAF in contrast to serous borderline tumors and low-grade serous carcinoma, furthermore, mucinous cystadenomas also has a mutation in KRAS." (PMID 35281584, 2022). "KRAS and BRAF mutations are not found in the early serous cystadenoma stage, but they have been detected in the APSTs and adjacent cystadenoma epithelium in serous cystadenomas associated with small APSTs." (PMID 27128903, 2016). "We aimed to identify genetic variations in KRAS, BRAF, PIK3CA, and ERBB2 in LGSC/SBT/serous cystadenomas (SCAs) in a Japanese population." (PMID 31892193, 2019). "Additionally, BRAF and KRAS mutations, which characterize serous borderline tumors (SBTs) and LGCSs, are absent in serous cystadenomas." (PMID 35326657, 2022).
Wilms tumor (8 papers, 2017 to 2025). An embryonal neoplasm characterized by the presence of epithelial, mesenchymal, and blastema components. "The remainders, two cases of PRCC and one case of Wilms tumor, which exerted similar morphological features with MA, were further identified by immunohistochemical study and BRAF mutations detection using qPCR." (PMID 30111351, 2018). "The genetic confirmation of MA, especially the detection of the BRAF V600E mutation, is essential for accurate diagnosis and management, particularly given its potential to be confused with more common renal tumors like Wilms tumor." (PMID 40248024, 2025). "Nephroblastoma generally does not harbour mutations of BRAF but tends toward other genetic alterations, including, but not limited to WT1 and CTNNB1 mutations." (PMID 40177273, 2025). "None of epithelial-predominant nephroblastomas was positive for BRAF mutation using either molecular or immunohistochemistry methods in current study." (PMID 28903326, 2017). "Previous investigations also found that nephroblastomas were negative for BRAF mutation by molecular assays." (PMID 28903326, 2017). "To date, there are no cases reported in literature of Wilms’ tumor exhibiting BRAF mutations." (PMID 33046021, 2020). "All cases of epithelial-predominant nephroblastoma were completely negative, correlating with their BRAF wild-type status." (PMID 28903326, 2017). "All epithelial-predominant nephroblastomas were BRAF-wild-type and none expressed VE1." (PMID 28903326, 2017). "Adult nephroblastoma is positive for WT1 but negative for CD57 and BRAF." (PMID 37550779, 2023).
ameloblastic carcinoma (7 papers, 2017 to 2023). A rare, cytologically malignant ameloblastoma that may metastasize. "In conclusion, we have uncovered a unique case of ameloblastic carcinoma associated with an alteration of Wnt signalling and the presence of BRAF mutation." (PMID 37573343, 2023). "However, BRAF p.V600E mutation has been recently reported in 5/5 ameloblastic carcinoma cases submitted to molecular screening." (PMID 35048058, 2021).
anaplastic ganglioglioma (7 papers, 2019 to 2024). A WHO grade III neuroepithelial neoplasm composed of neoplastic, mature ganglion cells and anaplastic glial cells. "MEK inhibition in conjunction with BRAF inhibition has shown promising results in BRAF V600E mutation in adult anaplastic ganglioglioma." (PMID 32999736, 2020). "Immunotherapies are spreading nowadays, especially targeting BRAF as an emerging adjuvant therapy in anaplastic ganglioglioma." (PMID 38539674, 2024). "Only 1 young patient with an anaplastic ganglioglioma was treated upfront with a BRAF inhibitor with a curative intent." (PMID 36567957, 2022). "All previously reported phenotypical anaplastic gangliogliomas WHO Grade III with H3 K27M genotype lacked BRAF V600E mutation." (PMID 32451719, 2020).
basal cell carcinoma (7 papers, 2015 to 2025). A carcinoma involving the basal cells. "It is interesting to note that the top known dysregulated pathways in BCC, like the hedgehog signaling pathway, basal cell carcinoma pathway, and Notch signaling pathway, had statistically significant interactions with STR somatic mutations in APC and BRAF." (PMID 40427167, 2025).
brain cancer (7 papers, 2014 to 2026). A primary or metastatic malignant neoplasm affecting the brain. "Use of BRAF inhibitors in pediatric brain cancers has been reported in a case report of pediatric brain stem ganglioglioma with a BRAF V600E mutation, where the patient was successfully treated with vemurafenib and vinblastine." (PMID 25563358, 2014). "Clinical trials are needed to investigate optimal targeted therapy for BRAF V600E mutant pediatric brain cancers." (PMID 25563358, 2014). "Importantly, in the context of BRAF mutant pediatric brain cancers where BRAF inhibition is already being tested, it should be feasible to quickly test this hypothesis in clinical trials." (PMID 28094001, 2017).
esophageal squamous cell carcinoma (7 papers, 2012 to 2024). Esophageal squamous cell carcinoma (ESCC) is a type of esophageal carcinoma (EC) that can affect any part of the esophagus, but is usually located in the upper or middle third. "Although preclinical study on efficacy of BRAF inhibitors is yet to be tested in esophageal SCC, prospective screening for the presence of BRAF mutation should be actively considered in esophageal SCC given the lack of treatment options for these patients." (PMID 22870241, 2012). "Using FFPEs, we successfully screened 80 metastatic esophageal SCC and have identified PIK3CA mutation (11.5%) and BRAF mutation (1.2%) as potential targets for further therapeutic development." (PMID 22870241, 2012). "We identified that 11% of metastatic esophageal SCC had PIK3CA mutations in exon 9 (E542K, E545K) and exon 20 (H1047R, L) and that 1% of the patients harbored BRAF V600E mutations." (PMID 22870241, 2012).
gliosarcoma (7 papers, 2011 to 2024). A rare histological variant of glioblastoma (WHO grade IV) characterized by a biphasic tissue pattern with alternating areas displaying glial and mesenchymal differentiation (WHO). "Gliosarcoma mutations with potential therapeutic indications include BRAF, EGFR, CDKN2A, NF1, and PTEN." (PMID 34504233, 2021). "Finding the BRAFV600E mutation opens a new possibility to treat gliosarcoma patients with targeted therapies against the mutated BRAF protein." (PMID 30818875, 2019). "However, BRAF V600E mutations were first described in a few case reports and later in a study applying next generation sequencing in 10 gliosarcomas, which revealed BRAF V600E mutations in 2 cases." (PMID 31181803, 2019). "Of the 19 common genes in gliosarcoma, five (BRAF, EGFR, CDKN2A, NF1, and PTEN) were indicated as potentially targetable genes present in the OncoKB database." (PMID 34504233, 2021). "Among the most frequently altered genes found in gliosarcoma, BRAF, EGFR, PTEN, NF1, and CDKN2A are potentially targetable according to OncoKB." (PMID 34504233, 2021). "In this patient’s case, acquired mutations in KRAS with oncogenic potential and NF1 with unknown actionability were observed after prolonged exposure to BRAF inhibition along with a morphological transformation to gliosarcoma." (PMID 37231247, 2023). "In our study, we observed BRAF to be altered in 10% of gliosarcomas, compared to 3% of GBMs." (PMID 34504233, 2021). "BRAF may thus be a therapeutic avenue for a subset of gliosarcomas as well." (PMID 34504233, 2021). "So far, no other BRAF mutations or fusions have been reported in gliosarcoma." (PMID 31181803, 2019). "In the context of existing and emerging therapies, the current study shows that PI3K and BRAF inhibitors could be useful in targeted therapy for gliosarcoma patients, and that the molecular profiling of gliosarcoma could be very helpful to find fitting clinical trials or the off-label use of drugs." (PMID 30818875, 2019). "Initial studies suggested that BRAF mutations are absent in gliosarcomas." (PMID 31181803, 2019). "We demonstrate that gliosarcoma bears somatic alterations in gene coding for PI3K/Akt (PTEN, PI3K) and RAS/MAPK (NF1, BRAF) signaling pathways that are crucial for tumor growth." (PMID 30818875, 2019). "We demonstrate that most gliosarcoma tumors have somatic alterations of PIK3/Akt (PTEN, PI3K) and RAS/MAPK (NF1, BRAF) signaling pathways that are crucial for tumor growth and therapy resistance." (PMID 30818875, 2019).
metanephric adenoma (7 papers, 2017 to 2025). A benign, well-circumscribed renal cortical neoplasm affecting females more often than males. "The hallmark of metanephric adenoma is the presence of the BRAF V600E mutation, seen in up to 90% of cases, which makes it useful diagnostically when attempting to differentiate these two tumours." (PMID 40177273, 2025). "Metanephric adenoma is more common in female patients in a 2: 1 ratio, just like in mutated BRAF MA." (PMID 35198098, 2022). "Only the mutational analysis demonstrated the presence of the BRAF V600K mutation (for the first time described in a case of metanephric adenoma), highlighting the necessity of sequencing in case of MA with negativity for BRAF VE1 clone." (PMID 33175195, 2021). "We sought to determine the clinical and morphologic features of BRAF-mutated metanephric adenoma and to correlate BRAF mutation with BRAF V600E immunohistochemical staining results." (PMID 28903326, 2017). "Recently, somatic mutation of the BRAF (v-raf murine sarcoma viral oncogene homolog B1) oncogene, located on the long arm of chromosome 7, was identified as a common event in metanephric adenomas." (PMID 28903326, 2017). "Attention to the association of BRAF mutation with metanephric adenoma has been drawn by a few case reports and small series." (PMID 28903326, 2017). "The current study, which tested 48 cases of metanephric adenoma for BRAF mutation, is the largest of its kind." (PMID 28903326, 2017). "In summary, we have identified distinct clinicopathologic patterns associated with BRAF-mutated metanephric adenoma." (PMID 28903326, 2017). "Moreover, KANK1 has been discovered to fuse with neurotrophic receptor tyrosine kinase 3 (NTRK3) gene in patient samples with pathologically confirmed metanephric adenoma leading to a subset of B-Raf proto-oncogene, serine/threonine kinase (BRAF) mutations." (PMID 37731134, 2023). "This intends that BRAF V600E mutations and regions of metanephric adenoma are more common in epithelial-predominant WT but not necessarily present in all epithelial-predominant WTs." (PMID 39148862, 2024).
polyp (7 papers, 2015 to 2024). A usually exophytic mass attached to the underlying tissue by a broad base or a thin stalk. "CIMP also seems to be more likely to develop when a BRAF mutation is present and the polyp is in the proximal colonic environment." (PMID 30071442, 2018). "In polyp group, BRAF gene mutation was most frequent (30.3%)." (PMID 31653137, 2019). "Furthermore, PRDM5 protein levels were substantially reduced across both serrated and conventional polyp types and more so in BRAF mutant and wild type cancers." (PMID 25613750, 2015). "Furthermore, BRAF mutant tumors were more prevalent in the no polyp group." (PMID 38978992, 2024). "While animals did not develop invasive cancer, and instead died due to polyp load, these data indicate that the commutation of APC and BRAF in an enterocyte induces rapid neoplastic alterations and an overt proliferative phenotype." (PMID 32384699, 2020).
Rosai-Dorfman disease (7 papers, 2014 to 2025). "Recent research has revealed that the development of Rosai-Dorfman disease (RDD) may be closely linked to specific genetic mutations, such as BRAF, KRAS, and NRAS involving in the abnormal activation of the MAPK/ERK signaling pathway." (PMID 40018414, 2025). "Genotyping of 69 histiocytic lesions revealed that 23/48 Langerhans cell lesions were BRAF-V600E-mutant whereas all non-Langerhans cell lesions (including dendritic cell sarcoma, juvenile xanthogranuloma, Rosai-Dorfman disease, and granular cell tumor) were wild-type." (PMID 24938183, 2014).
Spitz nevi (7 papers, 2011 to 2025). "The following year two papers challenged the notion that Spitz nevi lack BRAF mutations, showing that 21% (10 of 48) and 100% (8 of 8) of the specimens studied were indeed V600E BRAF positive." (PMID 21754924, 2011). "While BRAF V600E mutations have been described in congenital nevi, Spitz nevi, and blue nevi, they have been reported to occur with greatest frequency in acquired nevi." (PMID 21754924, 2011). "Indeed, a worrisome melanocytic lesion with Spitz nevus features should lack BRAF and NRAS mutations and harbor one of these typical initiating genetic drivers to be classified as AST or Spitz melanoma." (PMID 34830218, 2021). "Spitz nevi are known to be linked to somatic alterations in HRAS and 6q23, as well as to fusions and mutations in tyrosine kinases and serine/threonine kinases such as BRAF, MAP3K8, and MAP2K1." (PMID 39925532, 2025). "In the 220 Spitz nevi analyzed in these experiments, not one harbored a BRAF mutation." (PMID 21754924, 2011). "Consecutive to Spitz nevi exclusion, KRAS sensitivity was not changed (71.88%), whereas BRAF specificity was slightly higher (65.22%)." (PMID 34769348, 2021).